STON1-GTF2A1L (STON1-GTF2A1L readthrough)
Synonyms: SALF
Gene: Protein-coding gene on chromosome 2 (48,529,925 to 48,776,517, forward strand). Ensembl gene ENSG00000068781.
Genetic constraint (gnomAD): Loss-of-function variants: 109 observed, 98.72 expected, observed/expected ratio (o/e) 1.1, 90% interval 0.94 to 1.29. The synonymous counts are far from expectation, so gnomAD's model fits this gene poorly and the ratio says little. Missense variants: 1,762 observed, 1,313.9 expected, observed/expected ratio (o/e) 1.34, 90% interval 1.29 to 1.39. Synonymous variants: 566 observed, 468.05 expected, observed/expected ratio (o/e) 1.21, 90% interval 1.13 to 1.3.